IL1B (interleukin 1 beta)
Diseases named in the same sentence as IL1B in open-access papers (continued):
Sharing a sentence is not in itself a finding about the gene and the disease.
tumor (continued). "Moreover, dysregulated expression of TNF-α, IL-6, and IL-1β was closely associated with altered cellular microenvironments and tumor pathological progression." (PMID 41323840, 2025). "IL-1β may also contribute to cancer-related symptoms such as cancer cachexia and tumor-associated pain." (PMID 41007766, 2025). "Tumor‐associated macrophages (TAMs) could secrete IL‐1β or Lipocalin‐2 to promote lymphangiogenesis." (PMID 40135589, 2025). "Additionally, deconvolution analysis revealed a positive correlation between IL-1β expression and infiltration of tumor-associated neutrophils (TANs) and macrophages, contributing to chronic intestinal inflammation in CRC." (PMID 40019680, 2025). "In mice, adipocytes are able to secrete IL-1β, recruit tumor-associated neutrophils, and induce the activation of PSC, thereby promoting the proliferation of connective tissue, accelerating tumor growth, and weakening the therapeutic effect of chemotherapy drugs." (PMID 39948335, 2025). "In addition, the damage-associated molecular patterns (DAMPs) released by tumor cells after being killed by particles can activate macrophages and neutrophils, leading to abnormal upregulation of inflammatory factors such as IL-1β, IL-6, and TNF-α." (PMID 40740952, 2025). "The study also showed that IL-1β blockade could prevent particulate matter-induced tumor formation in mouse models with EGFR and KRAS mutations." (PMID 40940992, 2025). "Toll-like receptor 4 (TLR4) pathways and the NLRP3 inflammasome are aberrantly activated by pollutant components, leading to excessive IL-1β maturation and skewing alveolar macrophages towards a tumor-associated phenotype that supports immune evasion and tumor progression." (PMID 41345682, 2025). "Cytokines such as IL-1β and IL-6, secreted predominantly by tumor-associated macrophages and stromal cells, in concert with suboptimal concentrations of TME-derived TGF-β, drives Treg-to-Th17 reprogramming through Foxp3 suppression and impairment of regulatory function." (PMID 41181112, 2025). "Similarly, persistent overactivation of the IL-1β pathway has been linked to tumor promotion, highlighting the therapeutic potential of IL-1β inhibition in cancer prevention and treatment." (PMID 40670983, 2025). "Additionally, tumor-intrinsic inflammasome activation and IL-1β secretion have been implicated in shaping treatment responses, particularly by promoting resistance to targeted therapy and other anticancer interventions." (PMID 40558540, 2025). "Research has shown that activation of the AIM2 inflammasome in nasopharyngeal carcinoma leads to increased secretion of tumor-derived IL-1β, resulting in the recruitment of a significant population of tumor-associated neutrophils (TANs) and suppression of tumor growth in murine models." (PMID 39744568, 2025). "Furthermore, BRAF/MAPK pathway blockade is represented by inhibition of tumor-associated fibroblasts (TAFs) by modulation of interleukin-1 (IL-1), in particular by the transcription of IL-1α and IL-1β." (PMID 40872623, 2025). "Similarly, IL-1β, associated with tumor-promoting inflammation, was elevated in OLR liver tissue but was absent in the blood." (PMID 41006707, 2025). "This suggests that IL1RN editing may drive macrophages toward an inflammatory transcriptional program associated with ISG and IL1B monocyte identities, which is further amplified in the tumor context." (PMID 40668918, 2025). "An increase in the expression of IL-1β levels is associated with tumor progression." (PMID 40244135, 2025).
tumor (continued). "This evidence suggests that the effect of chloroquine in increasing the serum level of IL-1β could be associated with the inhibition of autophagy of cytokines for inflammatory cell activation in response to the presence of a tumor." (PMID 38774541, 2024). "The pro-tumorigenic role of IL-1β has been supported for many years, and its association with angiogenesis has also been shown to have a clear correlation in a wide range of tumors, manifested as enhanced angiogenesis and promotion of tumor progression." (PMID 38553639, 2024). "Nevertheless, in the tumoral environment, it behaves counterintuitively: in breast cancer, IL-1β is able to induce the recruitment of immunosuppressive cells such as tumor-associated macrophages (TAMs) and myeloid-derived suppressor cells (MDSCs), gaining advantages for neoplastic spread." (PMID 38607023, 2024). "Mutations in the IL1B protein can result in structural and functional alterations that might lead to tumor formation." (PMID 38858637, 2024). "IL1A encodes IL‐1α, which, along with IL‐1β, plays a dual role in malignant tumour progression." (PMID 39602465, 2024). "Thus, we detected which signaling pathway was associated with the ability of TNF-α and IL-1β to regulate tumor cells." (PMID 39726047, 2024). "Elevated levels of IL-1β have been linked to tumor invasion and metastasis." (PMID 39575419, 2024). "Pleiotropic effects of IL-1β variants in cancer may be confirmed because, in addition to the main pro-tumour activity, it can also have anti-tumour effects." (PMID 38867324, 2024). "TRIM8 could also mediate K63-linked ubiquitination of TAK1, hence activating TNF-α, IL-1β and NF-κB signaling, which cooperatively promote malignant phenotypes of tumor cells." (PMID 38879600, 2024). "Moreover, the activation of purinergic pathways culminates with the production of pro-inflammatory cytokines, such as IL-1β and IL-18, which contribute to an inflammatory microenvironment predisposing to tumor development." (PMID 39456655, 2024). "In addition to regulating lymphocytic infiltration, increased levels of tumor-derived IL-1β (with a threshold of 64.2 pg/ml in murine models) have been shown to recruit a plethora of tumor-associated neutrophils (TANs) to significantly suppress tumor growth." (PMID 39483474, 2024). "Additionally, we show that high tumor expression of IL-1β is associated with poorer outcomes in both DCIS and invasive TNBC, underscoring the critical role of this inflammatory axis in disease progression and prognosis." (PMID 39801513, 2024). "To elucidate the characteristics of myeloid cells or macrophages as a source of IL-1β, we assessed the status of tumor-associated macrophage (TAM) polarization according to the M1-macrophage or M2-macrophage phenotype by examining the expression of respective signature genes." (PMID 37441079, 2023). "Thus, tumor‐released lactate and Mφ‐derived IL‐1β mediated the crosstalk loop and caused immunosuppression." (PMID 37009412, 2023). "Currently, there is evidence that inflammatory cytokines and chemokines such as TNFα, IL-1β, and IL-6 may be produced by tumor cells and/or tumor-associated leukocytes and platelets and may directly contribute to malignant progression." (PMID 38137888, 2023). "This privileged IL-1β-IL1R1 link between macrophages and IL1R1+ iCAFs led us to investigate whether the IL-1β signaling triggered in CAFs could also push tumor-associated macrophages (TAMs) to a tumor-promoting (i.e. an M2-like) phenotype." (PMID 37460545, 2023). "IL-1β production by PDA-associated myeloid cells may also support tumor progression by promoting immune tolerance." (PMID 37081882, 2023). "In addition, NGL mice diploinsufficient in Il1b alleles were resistant to tumor-induced NF-κB activation." (PMID 36980752, 2023). "Increased expression of IL-1β associated with high IL-8 expression in macrophages might therefore contribute to the function of TAMs as a key tumor promoter in the TME." (PMID 37441079, 2023).
tumor (continued). "IL-1β is canonically produced by Kupffer cells and infiltrating macrophages during inflammation and can activate these structural cell species, as well as converting fibroblasts into tumor-associated fibroblasts recruiting innate immune cells." (PMID 37537225, 2023). "We set out to determine whether tumor genotype and/or timing of IL-1β inhibition (germline loss versus local tumor targeting) affect GBM growth in vivo by using GEMMs of de novo primary GBM." (PMID 37733448, 2023). "Research has shown that tumor-associated macrophages (TAMs) in the tumor microenvironment are primarily composed of M2-type macrophages, which promote the expression of IL-1α, IL-1β, VEGF-A, and VEGF-C, thereby facilitating tumor growth and tumor angiogenesis/lymphangiogenesis." (PMID 38235128, 2023). "Inflammatory cytokines, such as IL-1β and IL-18, and damage-associated molecular patterns (DAMPs) released during pyroptosis can reconfigure the immune microenvironment, activate tumor immunity, or even confer beneficial effects on tumorigenesis and cancer progression." (PMID 37511974, 2023). "Besides, NLRP3 activation and IL-1β secretion have been linked to tumor growth, invasiveness, relapse, and progression in recent studies." (PMID 37715239, 2023). "In addition, in tumor tissues, CM and especially its exosomes reduced the genes associated with inflammation including IL1β and NFκB, which express the anti-inflammatory effects of CM and its exosomes." (PMID 35493477, 2022). "Growth factors (G-CSF and granulocyte-macrophage colony-stimulating factor (GM-CSF)) and inflammatory cytokines (IL-6, IL-1β, and IL-17) produced by tumour cells, tumour-associated stromal cells, and tumour-infiltrating leukocytes (including T cells) can modulate haematopoiesis." (PMID 35860278, 2022). "In addition, IL-1β from tumor-associated macrophages (TAMs) can directly stimulate LEC proliferation and migration." (PMID 36612017, 2022). "The “seed and soil” theory postulates that tumor cells produce several tumor-associated factors, including interleukins (IL-1β, IL-6, IL-8, IL-11, IL-17), macrophage inflammatory protein 1α, TNFα, parathyroid hormone-releasing protein (PTHrP), and prostaglandin E (PGE2)." (PMID 36294305, 2022). "Also, it was found that Th17 cell count was positively related to the expression of IL-6, IL-17, and IL-1β cytokines and negatively associated with an increase in the number of metastatic lymph nodes and tumor cell angiogenesis." (PMID 35248028, 2022). "In contrast, chronic NLRP1 activation is responsible for persistent inflammation, which can be considered as tumor promoter in the skin, which might be mediated by inflammation-associated ROS and IL-1β." (PMID 36293159, 2022). "IL-1β deficiency inhibited blood monocytosis and reduced tumor expansion under HFHCD." (PMID 36104342, 2022). "IL-1β has already been implicated in the transition from chronic inflammation to tumor development." (PMID 35725836, 2022). "In mice, obesity-related inflammation causes an increase in IL-1β production, which then promotes angiogenesis and tumor progression by upregulating Angptl4, thereby setting the rationale for future exploitation of this factor as a potential therapeutic target for obese breast cancer patients." (PMID 36074318, 2022). "Similarly, IL‐1β deficiency in murine breast cancer model significantly represses the tumour progression while enhancing activated CD8+ lymphocytes." (PMID 36124714, 2022). "In addition, G-CSF, IL-6, VEGF, and IL1-β are among the cytokines produced by tumor and stromal cells that cause neutrophilia and make these neutrophils more suppressive." (PMID 36419156, 2022). "IL1β is also importantly associated with neutrophils, and IL1β-mediated antitumor effects depend on infiltrating immunostimulatory neutrophils, and tumor inflammasomes control tumor progression by recruiting neutrophils." (PMID 36686646, 2022).
tumor (continued). "Th1 cytokines, such as IL‐1β, IL‐2, IL‐12, IL‐18, TNFα, and IFNγ, are associated with proinflammation, while Th2 cytokines, such as IL‐4, IL‐5, and TGFβ, play a suppressive role in the tumour immune microenvironment." (PMID 35430766, 2022). "Those so-called cancer-associated adipocytes could then contribute to promoting tumor aggressiveness by over-expression of pro-inflammatory cytokines [interleukin (IL)-6, IL-1β] and vice versa." (PMID 35756650, 2022). "In particular, Interleukin-1β (IL-1β) stimulation led to a strong remodulation of chromatin accessibility, in part determined by the remodulation of genome methylation that in tumor cells is often associated with tumor progression." (PMID 36499741, 2022). "The association of M1-like macrophages with tumor metastasis may be partly due to the effects of inflammatory cytokines, such as IL-1β, TNF-α, and IL-6, which directly or indirectly contribute to vasoproliferation." (PMID 35844605, 2022). "Increased TNF-α signaling enhances the pro-oncogenic signaling pathways in epithelial cells through the Wnt/β-catenin pathway and NF-kB pathways, exacerbating the effects of proinflammatory cytokines in cancer-associated inflammation, especially IL-1β and IL-6, and accelerating tumor growth." (PMID 35884974, 2022). "Moreover, gastric cancer ascites scRNA-seq analysis suggested that IL-1R2-expressing tumor cells contributed in tuning tumor-associated macrophage-dependent IL-1β-mediated inflammation." (PMID 35211118, 2022). "Association between tumor-associated neutrophils (TANs) and metastases is apparently caused by the release of IL-1β, IL-6, IL-8, IL-17, and TNF-α, which induce the EMT process in gastric cancer cells by activation of cell signaling pathways such as JAK2/STAT3 and ERK1/2." (PMID 34503571, 2021). "In other words, which factor causes the tumor cells’ increased expression of IL1β?" (PMID 34066976, 2021). "Moreover, the enhanced aerobic glycolysis in Epstein–Barr virus (EBV)-associated nasopharyngeal carcinoma prompts tumour cells to produce high amounts of IL-1β and IL-6, both of which are responsible for MDSC functions." (PMID 34685679, 2021). "Further, corroborating our findings, LECs when treated with CCA-CM also showed increased gene expression of CXCL5 (p ≤ 0.0001) in addition to increased expression of critical inflammatory agents implicated in tumor-associated lymphangiogenesis such as IL1B, IL6, IL8." (PMID 34831316, 2021). "However, in pathophysiological statuses that from ongoing inflammatory states to CRC, the feedback loop malfunctions due to the excess of paracrine IL-1β produced by tumor microenvironmental cells, such as tumor-associated macrophages." (PMID 34667160, 2021). "Indeed, it has been shown that IL‐1β by intra‐tumoral injections is sufficient to cause CD8+ T cell‐mediated tumor regression in models of adenocarcinoma, melanoma, and sarcoma." (PMID 34459122, 2021). "In addition, tumor-associated macrophages isolated from lung tumor bearing mice exhibited increased production of IL-1β when stimulated with LPS plus ATP58." (PMID 33686176, 2021). "Chronic inflammation induced by the tumor, inflammatory cytokines such as soluble tumor necrosis factor (sTNF), interleukin 1 beta (IL-1β), TGF-β, and IL-10 cause myeloid cells to differentiate into MDSCs, which have been implicated in worsened prognosis, and resistance to CPI immunotherapy." (PMID 33477569, 2021). "Hindering IL1β-mediated crosstalk between fibroblasts and tumor cells might counteract inflammatory signaling, causing de novo resistance." (PMID 34066976, 2021). "The elevated tumor load was associated with decreased IL-1β and IL-18 levels." (PMID 33776057, 2021). "It is important to mention here that the activated tumor-associated macrophages may promote cancer progression by upregulating COX-2 in cancer cells via IL-1β auto amplification." (PMID 34588926, 2021). "IL-1β released from tumors is strongly implicated in tumor progression." (PMID 34577552, 2021).
tumor (continued). "Similarly, during initial stages of lung carcinogenesis in mice, tumor-associated macrophages were mainly pro-inflammatory (expressing IL-12 and IL-1β), and later transitioned to promote angiogenesis and tumor growth." (PMID 33441138, 2021). "Moreover, tumor-derived interleukin 1β (IL1β) has been associated with the conversion of fibroblasts into CAFs in squamous cell carcinoma." (PMID 34066976, 2021). "On the other hand, IL-1β can promote carcinogenesis by inducing chronic inflammation, endothelial cell activation, angiogenesis, or development of immunosuppressive cells, such as tumor-associated macrophages and myeloid-derived suppressor cells." (PMID 35097027, 2021). "Inflammasome activation in PAAD tumor cells may also regulate stromal cells, such as cancer-associated fibroblasts, through IL-1β/IL-1R." (PMID 34150748, 2021). "ASC deletion in myeloid cells was associated with significantly reduced IL-1β in the tumor." (PMID 32117971, 2020). "In addition, NLRP3 inflammasome in fibroblasts is further linked with progression and metastasis, and IL-1β was found to have an immunosuppressive, pro-tumorigenic in the tumor microenvironment." (PMID 32733479, 2020). "Damage-associated molecular patterns (DAMPs) released from dying tumor cells may regulate the synthesis of IL-1β and other cytokines; DAMPs also induce and sustain de novo anti-tumor T cell responses." (PMID 32973519, 2020). "IL-1β has been implicated in tumor growth, angiogenesis, invasiveness, relapse, and progression." (PMID 32397236, 2020). "On the contrary, IL-23 and IL-1β are associated to distant metastasis at diagnosis suggesting these cytokines may facilitate a pro-tumor inflammatory response engaged in tumor dissemination and aggressiveness." (PMID 32139737, 2020). "In a model of orthotopically introduced 4T1 BC cells, another cytokine, IL-1β, was studied, where its deficiency led to tumor regression in comparison to wild-type (WT) mice with tumor growth and metastasis along with heavy infiltration of the tumors by macrophages." (PMID 32784928, 2020). "The study revealed that 2-weeks of anakinra treatment alone could downregulate the expression of several genes for TLR and IL-1β families, but upregulate the expression of tumor lysis-associated genes like NK and CD8+ T-cells." (PMID 32733479, 2020). "Furthermore, high expressions of activated inflammasomes, IL-1β and IL-18, are also used as independent predictors of poor prognoses in ccRCC patients, while the tumor promoting cytokine, IL-6, has been implicated in the progression of RCC." (PMID 32714856, 2020). "However, in the serum of CLL patients, high levels of IL-6 were associated with low levels of IL-1β, which seems to lead to the development of tumor cells." (PMID 33228048, 2020). "Moreover, NLRP3 activation and IL-1β production are associated with tumor lymphangiogenesis and lung metastasis in BC." (PMID 33014808, 2020). "Moreover, when experiments are performed in IL-1β-deficient mice or using IL-1RA, the vascularization of the tumor was abrogated." (PMID 32635472, 2020). "Mechanistically, inhibition of PI3Kγ decreased TAM expression of genes associated with immune suppression and tumor angiogenesis (Arg1, Tgfb, Il1b, Il6, Vegfa), and upregulated expression of genes associated with anti-tumor immunity (Il12 and Ifng), suggesting TAM reprogramming." (PMID 33584701, 2020). "Tumor associated macrophages in the resting phase secrete immune-suppressive cytokine IL-10, while during activation by lipopolysaccharide (LPS), they secrete proinflammatory cytokines IL-1β, IL-6 and TNF." (PMID 32120819, 2020). "It encodes the IL-1B protein which affects multiple aspects of the tumour microenvironment." (PMID 31877723, 2019). "On the other hand, IL-1β production might be associated with anti-tumor capacity in some circumstances, which is consistent with our finding." (PMID 31766169, 2019).